MYCN (MYCN proto-oncogene, bHLH transcription factor)
Diseases named in the same sentence as MYCN in open-access papers (continued):
Sharing a sentence is not in itself a finding about the gene and the disease.
neuroblastoma (continued). "We previously developed a method for determining MYCN gene amplification status using cell-free DNA fragments released from cancer cells into the blood of patients with neuroblastoma (NB)." (PMID 27513929, 2016). "MiR-181c-5p is a known tumor suppressor in neuroblastoma: it belongs to the miR-181 family, whose members are known to be upregulated after MYCN silencing." (PMID 27829219, 2016). "Our first analyses were based on our previous findings and showed that acute exposure to cinacalcet triggers ER stress and apoptosis in CaSR-positive, MYCN-amplified neuroblastoma cells, dependent on phospholipase C activation." (PMID 26893368, 2016). "In examining the expression levels of the 13 differentiation-inducing miRNAs and MYCN mRNA in neuroblastoma specimens, we found that two miRNAs, miR-137 and miR-2110, are significantly anti-correlated with MYCN mRNA levels." (PMID 27764804, 2016). "Third, depletion of PRMT1 through siRNA knockdown reduced neuroblastoma cell viability and MYCN expression." (PMID 27571165, 2016). "Our results also identified the transcription factor complex YY1—which promotes neuroblastoma progression by interacting with MYCN —as regulated by ALK." (PMID 27732954, 2016). "It is noteworthy that similar levels of efficacy were demonstrated with the ABT-199/MLN8237 combination as the ABT-263/MLN8237 combination in the MYCN-amplified neuroblastoma cells." (PMID 26859456, 2016). "While Wnt inhibition reduced proliferation in all neuroblastoma cell lines it only reduced cells below pre-treatment numbers in the highest MYCN expressing cell lines, IMR32 and KCNR." (PMID 27531891, 2016). "Taken together, these data suggest that TFAP4 is required for the MYCN-driven neuroblastoma migration phenotype." (PMID 27448979, 2016). "In agreement, in an ALK/MYCN-driven mouse xenograft neuroblastoma model, brigatinib potently inhibited tumor growth, highlighting tumor inhibition efficacy in vivo." (PMID 27049722, 2016). "As such, augmenting treatment efficacy for this high-risk group will likely require the development of additional rational therapies based on targetable pathways specifically activated in neuroblastomas with MYCN amplification." (PMID 26859456, 2016). "In fact, we found that treatment with the TORC1/2 inhibitor MLN0128 led to downregulation of p-4E-BP1 and MCL-1 in MYCN-amplified neuroblastomas, which demonstrated that MCL-1 in these cancers is downregulated following inhibition of p4E-BP1." (PMID 26859456, 2016). "The negative correlation between MYCN expression and LEF1 and TCF7L2 expression seen in the cell lines was also observed in the neuroblastoma tumours, confirming the functional MYCN-Wnt interactions revealed in the cell line data." (PMID 27531891, 2016). "CCT137690, an inhibitor of both Aurora kinase A and B, inhibited cell proliferation in MYCN-amplified neuroblastoma cells and tumor growth in MYCN-driven transgenic tumors in vivo." (PMID 26771642, 2016). "In this study, we have demonstrated that TFAP4 is a direct transcriptional target of MYCN in neuroblastoma and that high levels of this transcription factor are associated with poor clinical outcome in this disease." (PMID 27448979, 2016). "The inhibitors 13-197, BI2536 and vismodegib showed cell growth inhibition with IC50 of 8.5-22.7 μM, 13-32.7 nM and 73.6-85.4 μM, against non-MYCN amplified neuroblastoma cells, respectively." (PMID 26934655, 2016). "Altogether, this combination should be prioritized for clinical testing in patients with the MYCN-amplified subset of neuroblastoma." (PMID 26859456, 2016). "MYCN-amplified neuroblastoma cell lines responded more potently to ABT199 than MYCN single copy cell lines, with IC50 values ranging from 10 nmol/L-20 μmol/L versus 10-18 μmol/L, respectively." (PMID 27056887, 2016).
neuroblastoma (continued). "To gain insight into the cellular and molecular consequences of NF1 loss in neuroblastoma, we used transgenic zebrafish models of neuroblastoma that overexpresses human MYCN in the PSNS." (PMID 27130733, 2016). "This was important as MYCN amplification and its overexpression in neuroblastoma tumors is one of the most powerful predictors of poor prognosis in neuroblastoma." (PMID 27678372, 2016). "SGO1 knockdown induced DNA damage in MYCN-overexpressing neuroblastoma cells, resulting in G2/M accumulation." (PMID 27539729, 2016). "CHK1 regulates the G1/S and G2/M checkpoints and is expressed at a significantly higher level in MYCN-amplified compared to MYCN-unamplified neuroblastoma." (PMID 26771642, 2016). "In vivo studies have provided direct evidences demonstrating that MYCN overexpression is an important driving force of neuroblastoma development." (PMID 27764804, 2016). "In order to investigate the molecular mechanisms of chemoresistance, we chronically exposed a MYCN-amplified human neuroblastoma cell line, isolated from a stage IV patient, to etoposide." (PMID 27683112, 2016). "Neuroblastomas are highly heterogeneous, with pathological type, disease stage, and MYCN amplification all influencing prognosis." (PMID 27732954, 2016). "We first calculated AGDEX scores of human SHH medulloblastomas and MYCN-amplified neuroblastomas with mouse medulloblastomas (Ptch1+/− model) and mouse neuroblastomas (Th-Mycn model), respectively." (PMID 26818002, 2016). "A major factor influencing neuroblastoma biology is the MYCN status in the tumor, which inversely correlated with CD9 expression in primary neuroblastomas." (PMID 27572323, 2016). "Loss of nf1 led to the aberrant activation of RAS signaling in MYCN-induced neuroblastoma, promoting both tumor cell survival and proliferation." (PMID 27130733, 2016). "In other words, in response to the pathologically elevated MYCN oncogenic pathway, the neuroblastoma cells activates the differentiation-inducing miRNA-mediated tumor suppressive pathway in order to prevent oncogenic transformation of the cells." (PMID 27764804, 2016). "We first identified genes correlated with either hASH1 or MYCN, the latter being a well-known proto-oncogene with clearly established prognostic value in neuroblastoma patients." (PMID 28066180, 2016). "First, MYCN-amplified neuroblastoma cells are exquisitely sensitive to the BCL-2/BCL-xL inhibitor ABT-263." (PMID 26859456, 2016). "Compared with the existing MYCN-driven mouse model of neuroblastoma, which expresses a human MYCN cDNA under the control of a rat tyrosine hydroxylase promoter, the novel LSL-MYCN;Dbh-iCre bears several advantages." (PMID 25174395, 2015). "Although TRPM7 overexpression did not affect proliferation of mouse N1E-115 neuroblastoma cells, others have suggested a role for TRPM7 in neuroblastoma cell proliferation, specifically in a MYCN-amplified context." (PMID 25797249, 2015). "Approximately half of poor prognosis neuroblastomas (NBs) are characterized by pathognomonic MYCN gene amplification and MYCN over‐expression." (PMID 25475372, 2015). "Targeted expression of MYCN to the peripheral neural crest of mice results in neuroblastoma tumors with high penetrance." (PMID 26029667, 2015). "Sensitivity of the present panel of neuroblastoma cell lines to RG7388 was analysed in relation to their MYCN, p14ARF and MDM2 status." (PMID 25844600, 2015). "Combined, these findings help explain the differing prognosis of neuroblastoma patients with elevated or amplified MYCN." (PMID 26673823, 2015). "Taken together, the novel LSL-MYCN;Dbh-iCre neuroblastoma mouse model overcomes the limitations of the only existing MYCN-driven neuroblastoma model, TH-MYCN." (PMID 25174395, 2015).
neuroblastoma (continued). "The significance of BLM, AHCY, PKMYT1, and CKS1B in the pathogenesis of neuroblastoma is indicated by their elevated expression in MYCN-amplified tumor samples and in MYCN-overexpressing cells and their correlation with poor patient survival." (PMID 25477524, 2015). "Combined pharmacological inhibition of MYCN and LSD1 through the use of small molecule inhibitors synergistically reduces MYCN-amplified Neuroblastoma cell viability in vitro." (PMID 26062444, 2015). "High SLC19A1 expression therefore appears to be a common feature of poor-outcome neuroblastoma, particularly in tumors with MYCN amplification." (PMID 25860940, 2015). "Correspondingly, MYCN upregulation promotes proliferation in many nervous system tumors and amplification of MYCN correlates with poor prognosis in neuroblastoma patients." (PMID 26222553, 2015). "From the CNAs mapped to the 13 MYCN-amplified neuroblastoma cell lines, we extracted those impacting the loci of differentially represented genes." (PMID 26399178, 2015). "We reasoned if GLS2 activity is indeed essential for glutamine-dependent anapleurosis in MYCN-amplified neuroblastoma cells, then, GLS2 suppression should recapitulate glutamine deprivation in regulation of glucose metabolism." (PMID 26528759, 2015). "Unexpectedly, we showed in the current study that MYCN-amplified neuroblastoma cells predominantly rely on activation of GLS2-mediated glutamine deamidation to sustain TCA cycle anapleurosis and biosynthetic activities." (PMID 26528759, 2015). "The current study extends these observations to demonstrate experimentally that MYCN-amplified neuroblastoma cell lines have increased folate requirements and are more sensitive to methotrexate treatment than their non-amplified counterparts." (PMID 25860940, 2015). "Inhibition of either the PI3K signaling pathway or the serine/threonine kinase AURKA was shown to decrease the stability of the MYCN protein and reduce the proliferation of neuroblastoma cell lines and xenografts." (PMID 26497213, 2015). "Collectively these results demonstrate that MYCN is a key driver of tumorigenesis in neuroblastoma, suggesting that therapeutic efforts aimed at inhibiting its expression/activity should have an important clinical relevance." (PMID 25477524, 2015). "MYCN-amplified neuroblastoma cells therefore appear to have a greater requirement for folates than their non-amplified counterparts." (PMID 25860940, 2015). "MYCN amplification occurs in 20% of neuroblastomas and is strongly related to poor clinical outcome." (PMID 25860940, 2015). "MYCN is a member of the MYC oncogene family originally identified in human neuroblastoma, and subsequently found to be expressed in the newborn murine adrenal gland." (PMID 26222553, 2015). "To identify the MYCN network in neuroblastoma we used a global, genome-wide approach in which we carried out an shRNA drop-out screen in isogenic cell lines expressing MYCN or not." (PMID 25477524, 2015). "We have previously shown that the epigenetic regulation of miR-183 in neuroblastoma involves MYCN and HDAC2 in the same complex." (PMID 25853389, 2015). "Given the frequent alteration of these genes in MYCN-amplified neuroblastoma genomic profiles, we studied the available cell lines assuming that translational control has a role in the phenotype of this tumor." (PMID 26399178, 2015). "To confirm that our findings in cell lines resemble that of MYCN-amplified neuroblastoma patient populations, we analyzed the microarray data obtained from 643 primary neuroblastoma tumors." (PMID 26528759, 2015).
neuroblastoma (continued). "Analysis of microarray data obtained from mouse neuroblastoma tumors bearing the human MYCN transgene further corroborated that GLS2 expression was significantly elevated during aggressive tumor progression." (PMID 26528759, 2015). "Second, our results support and extend the preclinical evidence indicating MLN8327 as a promising targeted therapeutic agent to treat MYCN-amplified neuroblastoma." (PMID 25174395, 2015). "In summary, these observations support the relevance of our new MYCN-driven mouse model for the study of human neuroblastoma." (PMID 25174395, 2015). "Subsequently, the dynamic regulation of MYCN-targeting miRNAs during neuroblastoma development was evaluated in a murine neuroblastoma progression model." (PMID 25294817, 2015). "MYCN is an important oncogene in the pathogenesis of neuroblastoma, and is known to regulate various cellular processes, including cell growth, cell proliferation, cell differentiation and apoptosis." (PMID 25351211, 2015). "In neuroblastoma, MYCN acts as a major oncogenic driver through pleiotropic effects regulated by multiple protein encoding genes as well as microRNAs (miRNAs)." (PMID 25294817, 2015). "We previously showed that MYCN-amplified neuroblastoma cells strictly rely on glutamine-dependent anapleurosis to maintain TCA cycle activity and cell viability." (PMID 26528759, 2015). "Here we report establishment of the first Cre-conditional human MYCN-driven mouse model for neuroblastoma that closely recapitulates the human disease with respect to tumor localization, histology, marker expression and genomic make up." (PMID 25174395, 2015). "We therefore sought to address these important questions in MYCN-amplified neuroblastoma cells and primary tumors." (PMID 26528759, 2015). "Previous studies have highlighted the importance of miRNAs in the regulation of MYCN, a major driver oncogene in neuroblastoma." (PMID 25294817, 2015). "We further demonstrate that these drugs have pre-therapeutic efficacy in models of MYCN-driven neuroblastoma and MYCN-driven medulloblastoma." (PMID 26029667, 2015). "Recently, it has been shown that inhibition of CDK4/6 by LEE011 reduces the growth of neuroblastoma tumors with MYCN amplification in murine xenograft models." (PMID 26225123, 2015). "We identified β-estradiol and MAPK/ERK as having functional cross-talk with MYCN and being novel targetable vulnerabilities of MYCN-amplified neuroblastoma." (PMID 26673823, 2015). "The two human neuroblastoma cell lines we used in the present study have been shown to differ in their expression of MYCN protein, which plays an important role in the synergistic activation of Smac in some neuroblastoma cells." (PMID 25889084, 2015). "Conversely, inhibition of MYCN by antisense approaches results in neuroblastoma regression in vivo and in vitro." (PMID 25477524, 2015). "We provide evidence that MYCN targeting miRNAs are preferentially downregulated in MYCN-driven neuroblastoma tumors, suggesting that MYCN negatively controls the expression of these miRNAs, and as such safeguards its own expression." (PMID 25294817, 2015). "In aggressive neuroblastoma, tumorigenesis is largely driven by amplification of the oncogene MYCN and/or structural aberrations of the genome, which are difficult to inhibit directly." (PMID 26497213, 2015). "About 20% of neuroblastoma patients have MYCN amplified (MNA) tumours, and are prone to treatment resistance, relapse, development of metastases and low survival." (PMID 26673823, 2015). "Two out of 12 MYCN-targeting miRNAs in neuroblastoma, miR-29a-3p and miR-29b-3p, showed significant reduction in expression 48h after MYCN activation." (PMID 25294817, 2015).
neuroblastoma (continued). "Using Cre expression driven by the Dbh promotor, which is active specifically in noradrenergic neurons of the peripheral and central nervous system, we restricted transgenic MYCN expression to the presumed tissue of neuroblastoma origin." (PMID 25174395, 2015). "We identified 29 miRNAs targeting MYCN, of which 12 miRNAs are inversely correlated with MYCN expression or activity in neuroblastoma tumor tissue." (PMID 25294817, 2015). "Amplification of the MYCN oncogene, which occurs in approximately 20–25% of human neuroblastomas, is the most prominent genetic marker of high-stage disease." (PMID 25174395, 2015). "Two of these miRNAs, miR-19a-3p and miR-19b-3p, are part of the oncogenic miR-17-92 cluster and were already known to be directly induced by MYCN in neuroblastoma cells." (PMID 25294817, 2015). "Initially, a study using the pan Aurora inhibitor CCT137690 showed that treatment of MYCN-amplified neuroblastoma cell lines inhibits cell proliferation and decreases MYCN protein expression." (PMID 26734566, 2015). "Of note, GLS2 is substantially upregulated in human neuroblastoma tumors harboring MYCN amplification, and correlates with increased malignancy in a mouse transgenic neuroblastoma model." (PMID 26528759, 2015). "Using a transgenic model of MYCN-amplified neuroblastoma and a model of medulloblastoma where murine-derived allografted cells are implanted into mice, we demonstrate significant in vivo efficacy against both neuroblastoma and medulloblastoma tumors." (PMID 26029667, 2015). "Taken together, these results support that N-Myc selectively activates GLS2 expression to promote glutamine catabolism in MYCN-amplified neuroblastoma cells." (PMID 26528759, 2015). "Pharmacological inhibition of either MYCN or LSD1 or combination of both drugs have significant effects in neuroblastoma cell cycle and viability partly through activation of apoptosis." (PMID 26062444, 2015). "To determine the effects of PW-12 treatment in vivo, we analyzed a genetically engineered mouse model for MYCN-driven neuroblastoma and a model of MYCN-driven medulloblastoma." (PMID 26029667, 2015). "al. observed a strong correlation between TRPM7 and MYCN expression levels in a large neuroblastoma patient cohort (Kocak, n = 649)." (PMID 25797249, 2015). "To prioritize candidates, we selected for further analyses genes whose products are inhibited by small molecule drugs, are direct targets of MYCN, and predict poor survival in neuroblastoma patients." (PMID 25477524, 2015). "Here, we show that PW-12, a bioavailable derivative of the PI3K inhibitor PIK-75, shows knockdown of MYCN in a neuroblastoma cell line with marked reduction in viability and changes in cell cycle consistent with a MYCN-specific effect." (PMID 26029667, 2015). "Our network-based approach identified vulnerable therapeutically targetable nodes that function as critical regulators or effectors of MYCN in neuroblastoma." (PMID 26673823, 2015). "We combined results from an unbiased and genome-wide high-throughput miRNA target reporter screen with miRNA and mRNA expression data from patients and identified 12 MYCN-targeting miRNAs in neuroblastoma tumor tissue." (PMID 25294817, 2015). "To this end, we performed miRNA expression profiling of the TH-MYCN mouse model, a murine MYCN-driven neuroblastoma progression model." (PMID 25294817, 2015). "Despite these advances, very little is known about the role of MYCN in the early steps of neuroblastoma initiation." (PMID 26222553, 2015). "Recent research has thus been focused on finding surrogate targets that assist MYCN in driving neuroblastoma." (PMID 26497213, 2015). "We reasoned that if GLS2-mediated glutamine deamidation is critical to the survival of MYCN-amplified neuroblastoma cells, then, depletion of GLS2 expression should achieve a phenotype similar to that caused by glutamine starvation." (PMID 26528759, 2015).